FN1 (fibronectin 1)
Description:
Fibronectins bind cell surfaces and various compounds including collagen, fibrin, heparin, DNA, and actin. Fibronectins are involved in cell adhesion, cell motility, opsonization, wound healing, and maintenance of cell shape. Involved in osteoblast compaction through the fibronectin fibrillogenesis cell-mediated matrix assembly process, essential for osteoblast mineralization (By similarity). Participates in the regulation of type I collagen deposition by osteoblasts (By similarity). Acts as a ligand for the LILRB4 receptor, inhibiting FCGR1A/CD64-mediated monocyte activation. [Anastellin]: Binds fibronectin and induces fibril formation. This fibronectin polymer, named superfibronectin, exhibits enhanced adhesive properties. Both anastellin and superfibronectin inhibit tumor growth, angiogenesis and metastasis. Anastellin activates p38 MAPK and inhibits lysophospholipid signaling. Secreted by contracting muscle, induces liver autophagy, a degradative pathway for nutrient mobilization and damage removal, and systemic insulin sensitization via hepatic ITGA5:ITGB1 integrin receptor signaling.
Synonyms: FN; CIG; MSF; LETS; GFND2; FINC; lnc-ABCA12-8; ED-B; FNZ; GFND; SMDCF
Tractability: Small molecule: a structure with a bound ligand is known; it has a binding pocket of medium quality. Antibody: a drug acting on it is in phase 2 or 3 trials; UniProt places it where antibodies can reach, with high confidence; its Gene Ontology location is reachable by antibodies, with high confidence; UniProt predicts a signal peptide or a membrane-spanning region. PROTAC: ubiquitination databases record sites on it; its protein half-life has been measured; a small molecule that binds it is known. Other modalities: an approved drug acts on it.
Target class: Adhesion
Gene: Protein-coding gene on chromosome 2 (215,360,440 to 215,436,120, reverse strand). Ensembl gene ENSG00000115414.
Subcellular location: Secreted, extracellular space, extracellular matrix; Secreted
Pathways (Reactome):
Disease: ALK mutants bind TKIs; Attachment of bacteria to epithelial cells; Paradoxical activation of RAF signaling by kinase inactive BRAF; Signaling by ALK fusions and activated point mutants; Signaling by BRAF and RAF1 fusions; Signaling by RAF1 mutants; Signaling by high-kinase activity BRAF mutants; Signaling by moderate kinase activity BRAF mutants; Signaling downstream of RAS mutants
Extracellular matrix organization: Degradation of the extracellular matrix; ECM proteoglycans; Fibronectin matrix formation; Integrin cell surface interactions; Molecules associated with elastic fibres; Non-integrin membrane-ECM interactions; Syndecan interactions
Signal Transduction: GPER1 signaling; GRB2:SOS provides linkage to MAPK signaling for Integrins; Integrin signaling; MAP2K and MAPK activation; MET activates PTK2 signaling; p130Cas linkage to MAPK signaling for integrins
Hemostasis: Cell surface interactions at the vascular wall; Platelet degranulation
Metabolism of proteins: Post-translational protein phosphorylation; Regulation of Insulin-like Growth Factor (IGF) transport and uptake by Insulin-like Growth Factor Binding Proteins (IGFBPs)
Cellular responses to stimuli: Turbulent (oscillatory, disturbed) flow shear stress activates signaling by PIEZO1 and integrins in endothelial cells
Developmental Biology: Developmental Lineage of Pancreatic Ductal Cells
Immune System: Interleukin-4 and Interleukin-13 signaling
Gene Ontology:
Molecular function: extracellular matrix structural constituent; identical protein binding; integrin binding; protease binding; protein binding; proteoglycan binding; signaling receptor binding; collagen binding; heparin binding; peptidase activator activity; receptor ligand activity
Biological process: biological process involved in interaction with symbiont; blood coagulation, fibrin clot formation; endodermal cell differentiation; endothelial cell migration; enteric nervous system development; integrin activation; integrin-mediated signaling pathway; negative regulation of monocyte activation; negative regulation of transforming growth factor beta production; neural crest cell migration; neural crest cell migration involved in autonomic nervous system development; positive regulation of cell population proliferation; positive regulation of fibroblast proliferation; positive regulation of gene expression; positive regulation of phosphatidylinositol 3-kinase/protein kinase B signal transduction; positive regulation of substrate-dependent cell migration, cell attachment to substrate; regulation of ERK1 and ERK2 cascade; regulation of protein phosphorylation; substrate adhesion-dependent cell spreading; cell adhesion; cell-matrix adhesion; cell-substrate junction assembly; heart development; nervous system development; response to wounding; and 1 more
Cellular component: blood microparticle; endoplasmic reticulum-Golgi intermediate compartment; extracellular exosome; extracellular matrix; extracellular region; fibrinogen complex; endoplasmic reticulum lumen; fibronectin fibril; non-collagenous component of basement membrane; non-collagenous component of interstitial matrix; plasma membrane; platelet alpha granule lumen; apical plasma membrane; basement membrane
Genetic constraint (gnomAD): Loss-of-function variants: 96 observed, 281.41 expected, observed/expected ratio (o/e) 0.34, 90% interval 0.29 to 0.4. The upper end of that interval is the gene's LOEUF score, 0.4, which puts it in group 1 of 6, group 1 being the genes least tolerant of losing a copy. Missense variants: 2,579 observed, 3,141.8 expected, observed/expected ratio (o/e) 0.82, 90% interval 0.79 to 0.85. Synonymous variants: 1,109 observed, 1,166.1 expected, observed/expected ratio (o/e) 0.95, 90% interval 0.9 to 1.
Gene-disease validity (ClinGen):
ClinGen rates the evidence that FN1 causes each of these diseases.
spondylometaphyseal dysplasia, 'corner fracture' type (autosomal dominant): Definitive. A type of skeletal dysplasia associated with short stature, developmental coxa vara, progressive hip deformity, simulated 'corner fractures' of long tubular bones and vertebral body abnormalities (mostly oval vertebral bodies).
glomerulopathy with fibronectin deposits 2 (autosomal dominant): Moderate.
Homologues: Orthologues: chimpanzee FN1 (99% identical), macaque FN1 (99% identical), dog FN1 (95% identical), pig FN1 (94% identical), guinea pig FN1 (93% identical), rat Fn1 (92% identical), rabbit FN1 (92% identical), mouse Fn1 (92% identical), tropical clawed frog fn1 (71% identical), zebrafish fn1a (58% identical), zebrafish fn1b (56% identical), Caenorhabditis elegans let-805 (22% identical). Paralogues in human: TNC (14% identical), TNXB (13% identical), TNR (12% identical), TNN (10% identical), ANGPT1 (5% identical), ANGPT2 (5% identical), ANGPTL1 (5% identical), FGB (5% identical), FNDC7 (4% identical), ANGPTL2 (4% identical), FGL2 (4% identical), FIBCD1 (4% identical), and 13 more.
Diseases named in the same sentence as FN1 in open-access papers:
FN1 is named in the same sentence as 479 diseases in open-access papers, as found by Europe PMC text mining. Sharing a sentence is not in itself a finding about the gene and the disease. The quoted sentences say what the papers report.
breast carcinoma (232 papers, 2005 to 2026). "Specifically, FN1 is frequently overexpressed in breast cancer and strongly linked to cancer recurrence and invasion." (PMID 40923764, 2025). "FN1 is recognized as a potential therapeutic target or clinical prognostic marker for breast cancer, as its heightened expression is closely associated with the metastasis and deterioration processes in breast cancer." (PMID 39471412, 2024). "In breast cancer, matrisome signatures associated with metastasis have been documented, highlighting FN1, Tenascin C, and lysyl oxidases as poor prognostic indicators." (PMID 38791926, 2024). "FN1 is implicated in several malignancies, including cervical cancer, gastric cancer, and breast cancer." (PMID 39911230, 2024). "We then consolidated an OPN pathway and upregulated gene signatures from our findings (Spp1, Timp3, Col11a1, Mmp9, Mmp2, Fn1, Cd44, and Il-4) to interrogate how their predicted activity is associated with relapse-free survival in breast cancer patients." (PMID 39448577, 2024). "In breast cancer, elevated FN1 expression has been linked to tumor invasiveness and metastasis, contributing to poor patient outcomes." (PMID 38913913, 2024). "FN1 were identified for the first time as cancer stromal key genes associated with breast cancer invasion and metastasis." (PMID 37607964, 2023). "This study demonstrates a potential connection between breast cancer, TB and endometriosis, and in this paper reported genetic variants of FN1 were identified as chemoresistance." (PMID 37607964, 2023). "Paradoxically, both fibronectin (Fn1) and Six1, glycoproteins in the extracellular matrix associated with more aggressive breast cancer phenotypes, were upregulated in UGDH KD." (PMID 37769033, 2023). "Mean mRNA levels of fibronectin 1 (FN1), a marker associated with an invasive and metastatic breast cancer phenotype and EMT in MCF7 cells, were 2.2 times higher in MB-KO cells than in WT cells." (PMID 36232784, 2022). "FN1, which is a multi-domain protein encoded by gene FN1located at the breast cancer susceptible locus 2q35, is actively engaged in cell adhesionand ECM organization and disassembly." (PMID 33884102, 2021). "In particular, FN1 was altered in 14 of 1020 breast cancer samples, where missense mutations accounted for 64%." (PMID 32818022, 2020). "For example, overexpression of FN1 is associated with tumor aggressiveness, metastasis, and poor prognosis of breast cancer." (PMID 32787954, 2020). "The results showed that FN1 was altered in 14 of 1020 breast cancer samples, where missense mutations accounted for 64%." (PMID 32818022, 2020). "High expression levels of COL1A1 and FN1 were associated with high grade or advanced stage of breast cancer and poor prognosis." (PMID 30237810, 2018). "The expression of FN1 is directly regulated by micro (mi)RNA-206, which has been demonstrated to be associated with metastatic cancer types, including breast cancer." (PMID 25824986, 2015). "Interestingly, alternatively spliced isoforms of MYO18 A and NFYA have been linked to prognosis in breast cancer patients, while FN1 is a critical component of the extracellular matrix that has been implicated in tumor progression and metastasis." (PMID 40316533, 2025). "finds that FN1 overexpression is associated with poor prognosis in breast cancer." (PMID 40438115, 2025). "Notably, these top-ranked genes have established associations with breast cancer, with studies indicating that the expression patterns of FN1 and IGKC correlate with patient survival and clinical outcomes." (PMID 38145948, 2023). "The main knots of interaction, analyzed by STRING, among genes products up-regulated in HER2-negative cells are known to be down-regulated in HER2-positive breast cancer, or have, in turn, been associated with triple-negative breast cancers, such as Fn1 and Vim." (PMID 34775465, 2021).
breast carcinoma (continued). "In patients with breast cancer and NSCLC, expression of FN1 and α5β1 was shown to be associated with poor prognosis, and in breast cancer expression of both MENA and MENAINV was significantly correlated with FN, and to a lesser degree with α5 in patients with worst prognosis." (PMID 29907768, 2018). "This includes upregulation of key ECM components such as fibrillar collagens and FN1, many of which are canonical targets of TGF-β signaling and are commonly associated with aggressive, invasive breast cancer behavior." (PMID 41231242, 2025). "Survival analysis showed that higher levels of BGN, FN1, COL11A1, and SPTBN1 are linked to poorer OS in patients with breast cancer." (PMID 40898538, 2025). "Higher levels of FN1 mRNA and protein was observed in breast cancer cell lines that also expressed high levels of AREG." (PMID 39995668, 2025). "Higher expression levels of BGN, FN1, COL11A1, and SPTBN1 are linked to poorer overall survival in breast cancer patients is noticeable." (PMID 40898538, 2025). "FN1 is required for the assembly of collagen I fibers and has been shown to induce epithelial to mesenchymal transition of HR+ breast cancer cells." (PMID 40847127, 2025). "FN1 and TGFβ was discovered to constitute positive reciprocal regulation loop in the prevention of cisplatin together with paclitaxel on breast cancer metastasis." (PMID 40638546, 2025). "Inhibition of the estrogen receptor is suggested to significantly decrease FN1 expression, consistent with studies demonstrating increased expression in breast cancer cells through G-protein coupled transmembrane receptors." (PMID 40182431, 2025). "The results revealed that MMP11+ mCAFs predominantly overlapped with FN1+ CAFs in breast cancer, COL11A1+ CAFs in colorectal cancer, and CTHRC1+ CAFs in lung adenocarcinoma." (PMID 40552583, 2025). "In human breast cancer tissues, FN1 is upregulated compared with normal tissues, and correlates with poor clinical outcomes." (PMID 39462388, 2024). "Consistent with previous reports demonstrating FN1 expression in endothelial cells in colorectal and breast cancer, our immunohistochemistry findings revealed that FN1 was primarily expressed in the perivascular regions in GBM." (PMID 38705944, 2024). "The ECM‐related genes, including MMP1, POSTN, and FN1, have shown higher expression in breast cancer, non‐small lung cancer, bladder cancer, and gastric cancer." (PMID 38639039, 2024). "The upregulated expression of the FN1 gene has been correlated with the development of breast cancer and poor prognosis." (PMID 37374977, 2023). "High expression of FN1 correlates with advanced pathological stage, T-stage, N-stage, and M-stage, predicting a poor prognosis in breast cancer patients." (PMID 38063927, 2023). "The expression level of FN1 has been correlated to an advanced stage of breast cancer and poor clinical outcomes." (PMID 37607964, 2023). "The expression data of ECM fiber-encoding genes (e.g., COL1A1, COL1A2, FGA, FGB, FGG, ELN, FN1, and VTN) from 1358 patients with breast cancer were used for Kaplan–Meier overall survival analysis." (PMID 37369642, 2023). "The prognostic effect of FN1 expression in breast cancer patients with restricted clinicopathological characteristics." (PMID 36035176, 2022). "FN1 is involved in the progression of various cancers, such as esophageal squamous cell carcinoma, breast cancer, colorectal carcinogenesis, and nasopharyngeal carcinoma." (PMID 35535385, 2022). "CREB3L1 acts as the downstream signal of PERK to regulate the expression of collagen I and FN1 and promote the invasion and metastasis of breast cancer." (PMID 36192735, 2022). "Summary of the Kaplan-Meier curve data for the nine hyper-methylation sites of FN1 in breast cancer." (PMID 36035176, 2022). "Recently Sahai and coauthors elegantly demonstrated that breast cancer cells metastasizing into the lung are induced to generate FN1 fibrils by their interaction with resident alveolar epithelial cells." (PMID 33731188, 2021).
breast carcinoma (continued). "Overexpression of FN1 has been observed in breast cancer, and it anticorrelates with poor prognosis in other cancer types." (PMID 33735170, 2021). "To investigate the relevance of our findings to progression of human breast cancer, we analyzed gene expression data of FN1 and two of its first-degree neighbours (PLAU and ALCAM), using data from The Cancer Genome Atlas (TCGA)." (PMID 34641959, 2021). "Exosomes derived from breast cancer cells target the lung fibroblasts and, upon their uptake, fibroblasts switch to an activated phenotype with FN1 deposition, ECM remodeling and pre-metastatic niche formation." (PMID 33731188, 2021). "A peptide that inhibits the interactions of α5β1-integrin with FN1 increases the apoptotic responses of breast cancer cell lines to ionizing radiation." (PMID 33731188, 2021). "They showed that FN1 enclosed into or absorbed on the surface of exosomes derived from breast cancer cells co-cultured with tumor-infiltrating leukocytes, favors exosome-dependent cancer cell invasion and tumor metastasis in the lung." (PMID 33731188, 2021). "In breast cancer, FN1 activates specific matrix metalloproteinases to promote breast cancer cell invasion and metastasis." (PMID 34276798, 2021). "Reduced CTGF expression led to increased CD44, SPARC, and FN1 expression in mesenchymal transformed breast cancer cells." (PMID 33087801, 2020). "Depleted plasma FN1 levels were observed in chronic lymphocytic leukemia and osteomyelosclerosis, whereas elevated plasma FN1 levels were found in breast cancer and gastric cancer." (PMID 32971853, 2020). "For example, miR-200b can target FN1 to regulate EMT in breast cancer cells exhibiting chemoresistance, and it can similarly suppress the growth of esophageal squamous carcinoma cells, inducing their cell cycle arrest." (PMID 32435616, 2020). "By inhibiting let-7g, breast cancer cell migration and invasion were promoted via the downregulation of Grb2-associated binding protein 2 (GAB2) and fibronectin 1 (FN1) expressions that led to subsequent activation of MAPK pathways." (PMID 30959863, 2019). "Different studies have identified FN1 in EVs secreted from trophoblasts, breast cancer-, melanoma-, neuroblastoma-, and CRC cells." (PMID 31454892, 2019). "BRC-31 breast cancer cells expressed high levels of cdh2, fn1 and vim and low levels of cdh1 and krt-8 compared to BRC-17, 32, 36 and 196 cells." (PMID 29382358, 2018). "Oncome analysis showed that the high expression levels of COL1A1 and FN1 correlated to an advanced stage of breast cancer and poor clinical outcomes." (PMID 30237810, 2018). "These high expression levels of COL1A1 and FN1 were correlated to late stage of breast cancer and poor clinical outcomes." (PMID 30237810, 2018). "An elevated FN1 level in breast cancer patients with recurrence or a metastatic event was observed in comparison with controls." (PMID 30237810, 2018). "In summary, breast cancer stroma-related genes, including JUN, FOS, ATF3, STAT1, COL1A1 and FN1, were all associated with tumor invasion and metastasis." (PMID 30237810, 2018). "Meta-analysis revealed that human breast carcinomas express elevated levels of Fibronectin (FN1) and VEGFA compared to normal tissues." (PMID 28977919, 2017). "In the breast cancer core network, we found Fibronectin 1 (FN1), which is related to migration; FLT4 involved in angiogenesis; GSK3B, an anti-proliferative enzyme; KPNA2, a nucleopore transporter and the EP300-associated transcriptional activator NCOA3." (PMID 28775339, 2017). "This analysis also revealed higher expression of cancer biomarkers such as KRT8 (breast cancer prognosis), FN1 (pancreatic cancer), NQ1 (lung cancer), and PSDM4 (liver cancer) in the Huh-7.4 cell line." (PMID 29221196, 2017). "We found that both COX-2 expression and activity concomitantly modulated TGFβ-promoted breast cancer cells stemness and expression of FN1, CDH2 and KRT14." (PMID 28054666, 2017).